SNORA74B (small nucleolar RNA, H/ACA box 74B)
Synonyms: U19-2
Gene: Small nucleolar RNA gene on chromosome 5 (173,020,728 to 173,020,928, forward strand). Ensembl gene ENSG00000212402.
Gene Ontology:
Biological process: RNA processing
Cellular component: nucleolus
Homologues: Orthologues: chimpanzee SNORA74 (99% identical), macaque SNORA74 (99% identical), chimpanzee SNORA74 (81% identical), tropical clawed frog SNORA74 (63% identical), tropical clawed frog SNORA74 (62% identical), tropical clawed frog SNORA74 (60% identical), tropical clawed frog SNORA74 (51% identical). Paralogues in human: SNORA74C-2 (90% identical), SNORA74C-1 (88% identical), SNORA74 (74% identical), SNORA74 (73% identical), SNORA74A (60% identical), SNORA74 (57% identical), SNORA74 (33% identical), SNORA74D (32% identical).